SMN1 (survival of motor neuron 1, telomeric)
Diseases named in the same sentence as SMN1 in open-access papers (continued):
Sharing a sentence is not in itself a finding about the gene and the disease.
spinal muscular atrophy (continued). "Spinal muscular atrophy (SMA) is a leading genetic disease affecting infants and children caused by deletions of or mutations in the Survival Motor Neuron 1 (SMN1) gene that codes for the multifunctional SMN protein." (PMID 41551726, 2026). "CNV detection in genes such as PMS2 (Lynch syndrome) and SMN1 (Spinal Muscular Atrophy) is notoriously challenging because of high-similarity paralogs (PMS2CL and SMN2) that cause nonspecific read alignment and distorted read depth." (PMID 41595524, 2026). "A prominent example is ASO therapy with Nusinersen for Spinal Muscular Atrophy (SMA; MIM 253300) caused by mutations in the SMN1 gene on chromosome 5." (PMID 41244709, 2025). "We further demonstrated the utility of this approach by establishing novel inducible and tissue-specific models of spinal muscular atrophy, opening new avenues for studying smn1-gene function and pathogenicity." (PMID 39831309, 2025). "Of note, SMN loss induced dwarfism and delayed endochondral ossification in Smn1 depletion-severe spinal muscular atrophy (SMA) mouse model and Smn1 chondrocyte conditional knockdown mouse." (PMID 41320719, 2025). "For example, Zolgensma, a gene therapy approved for spinal muscular atrophy (SMA), delivers a functional copy of the SMN1 gene via an adeno-associated virus (AAV) vector, restoring the production of survival motor neuron protein." (PMID 41235102, 2025). "Spinal muscular atrophy is a neuromuscular disorder characterized by a defect in the SMN1 gene, which destroys alpha neurons." (PMID 41008984, 2025). "Background and Objectives: Spinal muscular atrophy (SMA) is a progressive, autosomal recessive, rare neuromuscular disorder caused by a genetic defect in the SMN1 gene, where the SMN2 gene cannot sufficiently compensate." (PMID 40282862, 2025). "An ASO that disrupts spliceosome action on exon 7 of the survival motor neuron 1 (SMN1) gene and restores the gene to functioning length has been approved for the treatment of spinal muscular atrophy." (PMID 40268518, 2025). "We found reduced expression of SMN2 due to SMN1 conversion, potentially affecting spinal muscular atrophy, and increased expression of translocated duplications of AMY2B." (PMID 39149335, 2025). "Spinal muscular atrophy (SMA) is a degenerative neuromuscular condition resulting from a homozygous deletion of the survival motor neuron 1 (SMN1) gene in 95% of patients." (PMID 39846593, 2025). "For example, the ASO tofersen targets mutant SOD1 in ALS, while AAV-based delivery of SMN1 is used to treat spinal muscular atrophy (SMA)." (PMID 41585268, 2025). "Spinal muscular atrophy (SMA) is a genetic motor neuron disease caused by homozygous deletions or, less commonly, pathogenic single-nucleotide point mutations in the SMN1 gene." (PMID 41181835, 2025). "Spinal muscular atrophy (SMA) is a progressive, neurodegenerative disease caused by pathogenic variants in the survival motor neuron 1 (SMN1) gene on chromosome 5." (PMID 40089964, 2025). "Zolgensma (onasemnogene abeparvovec-xioi) followed in 2019, delivered a functional SMN1 gene to motor neurons with an AAV9 vector for patients with spinal muscular atrophy (SMA)." (PMID 41155416, 2025). "We did genetic testing, which showed a homozygous deletion of exon 7 of the SMN1 gene, with a heterozygous deletion in both parents, confirming a diagnosis of spinal muscular atrophy." (PMID 40364813, 2025). "A total of 426 patients were screened for spinal muscular atrophy—SMN1, and the carrier rate was 3.5%, and the detection rate of parents' co‐carrier was 0.5%." (PMID 38562051, 2024). "Spinal muscular atrophy (SMA) is a rare, autosomal, recessive, developmental disorder caused by the genetic loss or mutation of the gene SMN1 (survival of motor neuron 1)." (PMID 39264856, 2024). "Examples include targeting the HTT gene in Huntington’s disease or the SMN1 gene in spinal muscular atrophy." (PMID 39684197, 2024).
spinal muscular atrophy (continued). "Spinal muscular atrophy (SMA), which results from the deletion or/and mutation in the SMN1 gene, is an autosomal recessive neuromuscular disorder that leads to weakness and muscle atrophy." (PMID 38520738, 2024). "Mutations in the SMN1 gene, which encodes the survival motor neuron protein (SMN), are a primary cause of spinal muscular atrophy (SMA)." (PMID 39226164, 2024). "Spinal muscular atrophy (SMA) is a neuromuscular and neurodegenerative disease caused by the homozygous deletion of SMN1 exon 7 in 95% of cases." (PMID 39051406, 2024). "Mutations in the SMN1 gene, which encodes the SMN protein, give rise to the neuromuscular disorder spinal muscular atrophy (SMA)." (PMID 38318851, 2024). "The underlying cause of classic spinal muscular atrophy (SMA) is typically the homozygous absence or, less commonly, smaller mutations within the SMN1 gene located on chromosome 5." (PMID 39202360, 2024). "In neurodegenerative diseases, spinal muscular atrophy (SMA) was the first to be cured with the exogenous introduction of SMN1 gene to children under two years of age." (PMID 38396996, 2024). "Spinal muscular atrophy (SMA) is a rare progressive genetic neuromuscular disorder affecting spinal motor neurons, caused by defects in both copies of the SMN1 gene, leading to degeneration of alpha motor neurons in the anterior horn of the spinal cord." (PMID 39844848, 2024). "For example, onasemnogene abeparvovec (Zolgensma) treats spinal muscular atrophy (SMA) by delivering a functional SMN1 gene, while nusinersen (Spinraza) modifies SMN2 splicing to enhance functional protein levels." (PMID 39627904, 2024). "Spinal muscular atrophy (SMA) is an autosomal recessive disorder caused by deletion or/and mutation in the survival motor neuron 1 (SMN1) gene on chromosome 5." (PMID 37189623, 2023). "Newborn screening (NBS) assays for spinal muscular atrophy (SMA) typically use a polymerase chain reaction (PCR) based assay to identify individuals with homozygous deletion in exon 7 of the SMN1 gene." (PMID 36713073, 2023). "Spinal muscular atrophy (SMA) is a progressive, monogenic neuromuscular disorder caused by loss or disabling mutation of the survival motor neuron 1 (SMN1) gene that results in reduced amounts of SMN protein and motor neuron dysfunction." (PMID 36911944, 2023). "The SMN protein was initially characterized once mutations in its coding gene, SMN1 (OMIM *600354), were linked to motor neurons’ degeneration in spinal muscular atrophy (SMA)." (PMID 36675308, 2023). "One example is Spinal Muscular Atrophy (SMA), a degenerative MN disease caused by a deficiency of the Survival of Motor Neuron (SMN) protein due to mutations in the SMN1 gene." (PMID 38314348, 2023). "In spinal muscular atrophy (SMA), mutations in or loss of the Survival Motor Neuron 1 (SMN1) gene reduce full-length SMN protein levels, which leads to the degeneration of a percentage of motor neurons." (PMID 37108811, 2023). "LUXTURNA targets the RPE65 gene to treat inherited retinal dystrophy, while Zolgensma targets the SMN1 gene in motor neurons to treat spinal muscular atrophy." (PMID 37895887, 2023). "A commonly used mouse model of spinal muscular atrophy is the SMNΔ7 model in which the endogenous murine gene Smn1 is inactivated and replaced by two human genes, SMN2 and SMN2Δ7 (mSmn-/-; hSMN2+/+, hSMN2Δ7+/+)." (PMID 37936690, 2023). "Spinal Muscular Atrophy (SMA) is a severe neuromuscular disorder due to a defect in the survival motor neuron 1 (SMN1) gene." (PMID 36803361, 2023). "Gene therapy (e.g., onasemnogene abeparvovec for spinal muscular atrophy) used to deliver a functional copy of the SMN1 gene to replace the defective gene in spinal muscular atrophy (SMA) has shown clinical benefits." (PMID 38028604, 2023).
spinal muscular atrophy (continued). "For restoration of protein production affected by variants in monogenic disease, Nusinersen was approved for treatment of spinal muscular atrophy (SMA), an autosomal recessive neuromuscular disorder usually caused by variants in the SMN1 gene." (PMID 36678889, 2023). "Spinal muscular atrophy (SMA) is an autosomal recessive disease that is caused by mutations in SMN-2 and SMN-1 genes and causes problems in motor neurons." (PMID 36838970, 2023). "Spinal muscular atrophy (SMA) is a progressive, autosomal recessive, motor neuron disease, which is caused by mutations on chromosome 5 of the SMN1 gene." (PMID 37181426, 2023). "Spinal muscular atrophy (5q-SMA; SMA), a genetic neuromuscular condition affecting spinal motor neurons, is caused by defects in both copies of the SMN1 gene that produces survival motor neuron (SMN) protein." (PMID 36329412, 2022). "Mutations—point mutations and copy number changes—in the SMN1 and SMN2 genes cause a rare childhood disorder called spinal muscular atrophy (SMA) and SMN1 is one of the most-studied duplicated genes in the genome." (PMID 35680869, 2022). "For example, a homozygous deletion of the SMN1 gene results in a spinal muscular atrophy (SMA) phenotype, however asymptomatic individuals have also been reported having the same homozygous deletion as their affected siblings." (PMID 35672333, 2022). "Spinal muscular atrophy (SMA) is a severe neuromuscular disease (NMD) caused by deficiency of survival motor neuron (SMN) protein, due to homozygous loss of SMN1 gene function." (PMID 35189949, 2022). "An example is spinal muscular atrophy (SMA), an autosomal recessive neuromuscular disease caused by a mutation (usually a deletion) in the SMN1 gene, which codifies for the Survival Motor Neuron (SMN) protein." (PMID 35898644, 2022). "Spinal muscular atrophy (SMA), a common lethal genetic disorder in children, is caused by mutations or deletions in the survival of motor neuron 1 (SMN1) gene (MIM 600354), which leads to failure in encoding the SMN protein (UniProt accession number Q16637-1)." (PMID 36074806, 2022). "Spinal muscular atrophy (SMA) is a childhood motor neuron disease caused by mutations and deletions within the SMN1 gene." (PMID 35551393, 2022). "These patients were finally confirmed to have spinal muscular atrophy due to SMN1 deletion by polymerase chain reaction and restriction fragment length polymorphism." (PMID 36376972, 2022). "Given the need for clarity in practice, this review summarizes several clinically relevant variants in the SMN1 and SMN2 genes, including how they inform outcomes for spinal muscular atrophy carrier risk and disease prognosis." (PMID 36140824, 2022). "Zolgensma®, an AAV9 vector expressing functional SMN1, has received approval in the United States and other countries as the first CNS-targeting gene therapy for patients with spinal muscular atrophy (SMA)." (PMID 36320416, 2022). "Spinal muscular atrophy (SMA) is an autosomal recessive disease resulting from deletion of the SMN1 gene in the vast majority of cases." (PMID 36579590, 2022). "Spinal muscular atrophy (SMA) is an autosomal recessive neuromuscular disease, which is caused by mutations in the SMN1 gene." (PMID 35650592, 2022). "Spinal muscular atrophy (SMA) is a rare, recessively inherited neuromuscular disorder caused by deletions or mutations in the survival motor neuron 1 gene (SMN1), and the severity is modified by the number of SMN2 copies." (PMID 35578241, 2022). "For example, nusinersen is a splice-switching oligonucleotideapproved for the treatment of spinal muscular atrophy (SMA), a geneticdisorder caused by mutations to the SMN1 gene and inefficient productionof survival motor neuron (SMN) protein." (PMID 36711092, 2022). "Spinal muscular atrophy (SMA) is a form of motor neuron disease affecting primarily children that is caused by mutations and deletions within the survival motor neuron 1 (SMN1) gene." (PMID 36089582, 2022).
spinal muscular atrophy (continued). "Spinal muscular atrophy (SMA) is a rare autosomal recessive neurodegenerative disease, caused by homozygous disruption of the survival motor neuron 1 (SMN1) gene by deletion, conversion, or mutation and leading to muscle wasting and proximal muscle weakness." (PMID 35854387, 2022). "Such targeted methods have already been applied successfully to some difficult regions, such as repeat expansions and the SMN1 gene responsible for spinal muscular atrophy." (PMID 33462347, 2021). "Spinal muscular atrophy (SMA) results from the absence or mutation of SMN1, plus the inability of SMN2 to compensate for the loss of SMN1 due to exon seven jumping." (PMID 34630514, 2021). "A severe neurogenic disease, spinal muscular atrophy (SMA), is caused by the loss or mutation of SMN1 that specifically occurred in humans." (PMID 33440839, 2021). "Spinal muscular atrophy (SMA) is a rare, progressive neuromuscular disease (NMD), arising from loss-of-function mutations of survival motor neuron 1 (SMN1) gene." (PMID 34445667, 2021). "Nusinersen (FDA approval in December 2016) is used to treat spinal muscular atrophy (SMA), which is caused by deletions or mutations in the survival motor neuron 1 (SMN1) gene." (PMID 33816449, 2021). "Other formulations include Zolgensma® which brings a functional copy of the SMN1 gene to treat patients with spinal muscular atrophy." (PMID 34451862, 2021). "Some examples for CNS disorders include an AAV2 gene therapy designed to express RPE65 in the eye to treat Leber Congenital Amaurosis (Luxturna®) and an AAV9 vector that expresses SMN1 in motor neurons to treat Spinal Muscular Atrophy (Spinaraza®)." (PMID 34291049, 2021). "Spinal muscular atrophy (SMA) is a genetic neuromuscular disorder, due to mutations in the survival of motor neuron 1 (SMN1) gene with an incidence of about 1 in 11,000 live births." (PMID 33530934, 2021). "The technology allowed obtaining remarkable results in patients affected by spinal muscular atrophy (SMA), a childhood neuromuscular disease caused by the deletion or mutation of survival of motor neuron 1 (SMN1)." (PMID 33801336, 2021). "Spinal muscular atrophy (SMA) is a motor neuron disease, typically resulting from loss-of-function mutations in the survival motor neuron 1 (SMN1) gene." (PMID 33060681, 2020). "At similar age, an intravenous infusion of AAV9 particles packaging the SMN1 gene resulted in extended survival and improved motor functions in infants suffering for spinal muscular atrophy." (PMID 32207685, 2020). "Spinal muscular atrophy (SMA) is a common and lethal autosomal recessive neurodegenerative disease caused by mutations in the survival motor neuron 1 (SMN1) gene." (PMID 32552676, 2020). "A profound example of nearly unmappable CDS regions with high clinical relevance are the SMN1 and SMN2 genes, mutations in which cause spinal muscular atrophy (SMA) - a fatal neurological disorder with an early age of onset." (PMID 32029882, 2020). "The interplay between torsinA LOF and torsinB levels is reminiscent of spinal muscular atrophy (SMA), a disease linked to LOF of the SMN1 gene." (PMID 32202496, 2020). "Beyond ALS, FGF signaling has also been implicated in spinal muscular atrophy (SMA), a related motor neurodegenerative disease caused by loss of SMN1 function." (PMID 32302304, 2020). "Spinal muscular atrophy (SMA) is the leading genetic cause of death in young children, arising from homozygous deletion or mutation of the survival motor neuron 1 (SMN1) gene." (PMID 32501283, 2020). "Spinal muscular atrophy (SMA) is a genetic and autosomal recessive motor neuron disease caused by a homozygous deletion in the survival motor neuron 1 (SMN1) on chromosome 5q13." (PMID 32604776, 2020). "Preimplantation genetic testing for the monogenic disorder (PGT-M) spinal muscular atrophy (SMA) is significantly improved by supplementation of SMN1 deletion detection with marker-based linkage analysis." (PMID 31781167, 2019).
spinal muscular atrophy (continued). "SMN1 and SMN2 are camouflaged by each other, where both genes are known to contribute to spinal muscular atrophy, and have been implicated in ALS." (PMID 31104630, 2019). "Spinal muscular atrophy, SMA SMA is an autosomal recessive neuromuscular disease affecting 1 in 6000–10,000 live births, predominantly caused by loss of function of the SMN1 gene." (PMID 31203387, 2019). "In infants, the predominant MND is spinal muscular atrophy (SMA), typically an autosomal recessive condition caused by inactivating mutations in the survival motor neuron 1 (SMN1) gene that are partly counteracted by the paralogous SMN2 gene." (PMID 31822699, 2019). "Spinal muscular atrophy (SMA) is a leading genetic cause of pediatric mortality, in which homozygous loss or mutation of survival motor neuron 1 (SMN1) gene occurred." (PMID 31295920, 2019). "The first approach is used in the therapy of spinal muscular atrophy (SMA), autosomal recessive disorder in 95% of cases caused by homozygous deletion of exon 7 of the SMN1 gene." (PMID 29680930, 2018). "The ICV injection of AAV9 vector in SMNΔ7 mice, a severe model of spinal muscular atrophy, allowed to express a codon-optimized human SMN1 coding sequence in the spinal cord, which as a result, has improved significantly their survival." (PMID 30510219, 2018). "Spinal muscular atrophy (SMA) is a recessive autosomal neuromuscular disease, due to homozygous mutations or deletions in the telomeric survival motoneuron gene 1 (SMN1)." (PMID 29259166, 2017). "OSTF1 has also been demonstrated to interact with Survival of Motor Neuron 1 and 2 (SMN1 and SMN2 respectively), the loss of which leads to spinal muscular atrophy." (PMID 28936620, 2017). "Spinal muscular atrophy linked to chromosome 5q (SMA) is a recessive, progressive, neuromuscular disorder caused by bi-allelic mutations in the SMN1 gene, resulting in motor neuron degeneration and variable presentation in relation to onset and severity." (PMID 28676062, 2017). "In spinal muscular atrophy (SMA), degeneration of motor neurons causes progressive muscular weakness, which is caused by homozygous deletion of the SMN1 gene." (PMID 28634652, 2017). "For example, mice, which lack the SMN1 RNA binding protein and act as a model for human spinal muscular atrophy (SMA), survived twice as long on a pure C57BL/6N background than on the R7W-Tyro3-carrying FVB/N background." (PMID 28093506, 2017). "Loss of SMN1 leads to an SMN deficit, resulting in spinal muscular atrophy (SMA), a devastating genetic disease of children and infants." (PMID 29187847, 2017). "Spinal muscular atrophy (SMA), characterized by specific degeneration of spinal motor neurons, is caused by mutations in the survival of motor neuron 1, telomeric (SMN1) gene and subsequent decreased levels of functional SMN." (PMID 26586529, 2016). "Spinal muscular atrophy (SMA), a leading genetic disease of children and infants, is caused by mutations or deletions of Survival Motor Neuron 1 (SMN1) gene." (PMID 27481219, 2016). "Here the authors provide a system for heritable miRNA-mediated knockdown and demonstrate tunable silencing of the smn1 gene that recapitulate different forms of spinal muscular atrophy." (PMID 26051838, 2015). "Using this approach, we reproduce spinal muscular atrophy (SMA) in zebrafish by targeting the smn1 gene." (PMID 26051838, 2015). "Spinal muscular atrophy (SMA) is a childhood motor neuron disease caused by mutations and deletions within the survival motor neuron 1 gene (SMN1)." (PMID 26374403, 2015). "Genetic tests performed before WES excluded Huntington’s disease (IT15), spinal muscular atrophy (SMN1), spinal bulbar muscular atrophy (AR), primary torsion dystonia (DYT1), and the common forms of spastic paraplegias (SPG4, REEP1, ATL1, SPG7)." (PMID 25957632, 2015).